ENSG00000287264 (novel transcript)
Synonyms: LOC102723575
Gene: Long non-coding RNA gene on chromosome 11 (59,537,399 to 59,561,838, forward strand). Ensembl gene ENSG00000287264.
Gene Ontology:
Molecular function: triplet codon-amino acid adaptor activity
Biological process: translation